ZNF205 (zinc finger protein 205)
Description:
Transcriptional repressor involved in regulating MPV17L expression. By regulating MPV17L expression, contributes to the regulation of genes involved in H(2)O(2) metabolism and the mitochondrial apoptotic cascade.
Synonyms: RhitH; ZNF210; Zfp13
Tractability: PROTAC: UniProt records ubiquitination sites on it.
Gene: Protein-coding gene on chromosome 16 (3,112,550 to 3,120,527, forward strand). Ensembl gene ENSG00000122386.
Subcellular location: Nucleus
Subcellular location (Human Protein Atlas): Nucleoplasm
Pathways (Reactome):
Gene expression (Transcription): Generic Transcription Pathway
Gene Ontology:
Molecular function: protein binding; DNA-binding transcription factor activity, RNA polymerase II-specific; RNA polymerase II cis-regulatory region sequence-specific DNA binding; zinc ion binding; DNA-binding transcription repressor activity, RNA polymerase II-specific; RNA polymerase II transcription regulatory region sequence-specific DNA binding
Biological process: negative regulation of transcription by RNA polymerase II; positive regulation of hydrogen peroxide biosynthetic process; positive regulation of mitochondrial outer membrane permeabilization involved in apoptotic signaling pathway; regulation of DNA-templated transcription; regulation of transcription by RNA polymerase II
Cellular component: nucleus
Genetic constraint (gnomAD): Loss-of-function variants: 30 observed, 51.76 expected, observed/expected ratio (o/e) 0.58, 90% interval 0.43 to 0.79. The upper end of that interval is the gene's LOEUF score, 0.79, which puts it in group 3 of 6, group 1 being the genes least tolerant of losing a copy. Missense variants: 801 observed, 764.99 expected, observed/expected ratio (o/e) 1.05, 90% interval 0.99 to 1.11. Synonymous variants: 372 observed, 330.84 expected, observed/expected ratio (o/e) 1.12, 90% interval 1.03 to 1.23.
Homologues: Orthologues: chimpanzee ZNF205 (99% identical), macaque ZNF205 (95% identical), dog ZNF205 (79% identical), pig ZNF205 (78% identical), rabbit ZNF205 (75% identical), guinea pig ZNF205 (74% identical), mouse Zfp13 (69% identical), rat Zfp13 (64% identical). Paralogues in human: ZNF263 (32% identical), ZNF397 (26% identical), ZSCAN25 (26% identical), ZKSCAN8 (26% identical), ZSCAN30 (26% identical), ZSCAN22 (25% identical), ZKSCAN1 (25% identical), ZNF394 (25% identical), ZSCAN26 (24% identical), ZKSCAN3 (24% identical), ZKSCAN4 (23% identical), ZSCAN12 (23% identical), and 18 more.
Diseases named in the same sentence as ZNF205 in open-access papers:
ZNF205 is named in the same sentence as 8 diseases in open-access papers, as found by Europe PMC text mining. Sharing a sentence is not in itself a finding about the gene and the disease. The quoted sentences say what the papers report.
asthma (1 paper, 2025). "Among these genes, VMP1, ZNF205, ZNF205, and LGALS3BP showed significant reductions (p < 0.05) in expression between the healthy and asthma groups." (PMID 39858200, 2025).
breast carcinoma (1 paper, 2019). "For breast cancer, the number of KRAB‐ZNF‐positive samples was slightly different: (ZNF205 – 6/11, ZNF320 – 10/10, ZNF485 – 11/11, ZNF643 – 11/11, ZNF695 – 12/12, ZNF 707 – 10/10, and ZNF789 – 2/12)." (PMID 30444046, 2019). "In the breast cancer tissue panel (normal = 5, tumor = 43), we found that four KRAB‐ZNFs (ZNF205, ZNF273, ZNF485, ZNF695) were significantly upregulated in tumor tissue." (PMID 30444046, 2019).
familial Mediterranean fever (1 paper, 2023). Familial Mediterranean fever (FMF) is an autoinflammatory disorder characterized by recurrent short episodes of fever and serositis resulting in pain in the abdomen, chest, joints and muscles. "Zinc finger protein 205 (ZNF205) was first identified during the cloning of the gene for familial Mediterranean fever (FMF)." (PMID 37580950, 2023).
lung carcinoma (1 paper, 2019). "The smallest significant difference was noticed for ZNF205 in lung cancer (LUAD: FC = 1.4, P < 0.01; LUSC: FC = 1.3, P < 0.01; t‐test with Tukey HSD correction) and ZNF320 in BRCA (FC = 1.1, P < 0.001; t‐test with Tukey HSD correction)." (PMID 30444046, 2019). "In lung cancer tissue samples, KRAB‐ZNF staining was positive for at least four analyzed tumor samples (ZNF205 – 4/12, ZNF320 – 10/10, ZNF485 – 11/11, ZNF643 – 10/11, ZNF695 – 8/9, ZNF 707 – 10/11) and at least one sample from each set presented nuclear localization of a given factor." (PMID 30444046, 2019).
viral infection (1 paper, 2023). "Since IFN-β signaling is essential for host defense against viral infection, we further evaluated the influence of ZNF205 deficiency on viral infection and replication." (PMID 37580950, 2023). "Among the reports already available about ZNF205, no report is relevant to viral infection." (PMID 37580950, 2023).
ZNF205 also shares sentences with these, for which no sentence is quoted: cancer (2 papers); tumor (2); melanoma (1).